IFT80 (intraflagellar transport 80)
Description:
Component of the intraflagellar transport (IFT) complex B, which is essential for the development and maintenance of motile and sensory cilia.
Synonyms: KIAA1374; WDR56; FAP167; CFAP167; ATD2; SRTD2
Tractability: PROTAC: ubiquitination databases record sites on it.
Gene: Protein-coding gene on chromosome 3 (160,256,986 to 160,400,357, reverse strand). Ensembl gene ENSG00000068885.
Subcellular location: Cytoplasm; Cytoplasm, cytoskeleton, cilium basal body; Cytoplasm, cytoskeleton, cilium axoneme
Pathways (Reactome):
Organelle biogenesis and maintenance: Intraflagellar transport
Gene Ontology:
Molecular function: protein binding
Biological process: cilium assembly; intraciliary anterograde transport
Cellular component: intraciliary transport particle A; intraciliary transport particle B; centrosome; ciliary tip; cilium; 9+0 non-motile cilium; axoneme; ciliary basal body; cytoplasm; intraciliary transport particle
Genetic constraint (gnomAD): Loss-of-function variants: 32 observed, 58.15 expected, observed/expected ratio (o/e) 0.55, 90% interval 0.41 to 0.74. The upper end of that interval is the gene's LOEUF score, 0.74, which puts it in group 3 of 6, group 1 being the genes least tolerant of losing a copy. Missense variants: 504 observed, 609.8 expected, observed/expected ratio (o/e) 0.83, 90% interval 0.77 to 0.89. Synonymous variants: 199 observed, 205.41 expected, observed/expected ratio (o/e) 0.97, 90% interval 0.86 to 1.09.
Gene-disease validity (ClinGen):
ClinGen rates the evidence that IFT80 causes each of these diseases.
asphyxiating thoracic dystrophy 2 (autosomal recessive): Definitive.
Homologues: Orthologues: macaque IFT80 (99% identical), chimpanzee IFT80 (97% identical), dog IFT80 (96% identical), pig IFT80 (96% identical), rabbit IFT80 (95% identical), mouse Ift80 (95% identical), rat Ift80 (94% identical), guinea pig IFT80 (82% identical), tropical clawed frog ift80 (77% identical), zebrafish ift80 (74% identical), Caenorhabditis elegans che-2 (40% identical), Drosophila melanogaster Oseg5 (35% identical). Paralogues in human: TRIM59 (7% identical).
Diseases named in the same sentence as IFT80 in open-access papers:
IFT80 is named in the same sentence as 26 diseases in open-access papers, as found by Europe PMC text mining. Sharing a sentence is not in itself a finding about the gene and the disease. The quoted sentences say what the papers report.
Jeune asphyxiating thoracic dystrophy (10 papers, 2012 to 2023). "IFT80 mutants underlie Jeune syndrome, an autosomal recessive disease characterized by the constricted thoracic cage, respiratory insufficiency, cystic renal disease, polydactyl disease and retinal degeneration." (PMID 33957996, 2021). "Mutations in IFT80 causes Jeune asphyxiating thoracic dystrophy (JATD) and short rib polydactyly (SRP) type III." (PMID 30453504, 2018). "IFT80 is an IFT protein in IFT complex B. Mutations with reduced expression of IFT80 in human cause Jeune asphyxiating thoracic dystrophy (JATD) and short rib polydactyly type III (SRPIII)." (PMID 26996322, 2016). "Mutations of IFT80 in human have been identified in Jeune asphyxiating thoracic dystrophy (JATD) and short-rib polydactyly (SRP) syndrome type III." (PMID 26098911, 2015). "Partial loss of IFT80 function leads Jeune asphyxiating thoracic dystrophy (JATD) or short-rib polydactyly (SRP) syndrome type III, displaying narrow thoracic cavity and multiple cartilage anomalies." (PMID 26098911, 2015). "Mutation of IFT80, a component of the anterograde transport complex B, has also been demonstrated to cause Jeune syndrome." (PMID 24009529, 2013). "Recently, mutations in IFT80 have been found in patients with Jeune asphyxiating thoracic dystrophy and in mice." (PMID 22384377, 2012). "Additionally, we observed a novel association of LCA phenotype with IFT80 known to cause Jeune syndrome." (PMID 33957996, 2021). "Similarly, Sensenbrenner and Jeune syndromes appear to be milder presentations of the embryonically lethal short rib polydactyly syndrome as IFT80, WDR35 and DYNC2H1 are mutated in both milder and more severe phenotypes." (PMID 22829176, 2013). "IFT80 is a newly defined IFT protein and partial mutation of IFT80 in humans causes diseases such as Jeune asphyxiating thoracic dystrophy (JATD) and short rib polydactyly (SRP) type III, both characterized by abnormal skeletal development." (PMID 30453504, 2018). "Missense mutations in IFT80, which encodes an IFT-B2 subunit, have been identified in individuals with the skeletal ciliopathies Jeune asphyxiating thoracic dystrophy (JATD) as well as Verma-Naumoff syndrome, but it is still unclear how these alterations affect protein function." (PMID 29658880, 2018).
ciliopathies (4 papers, 2015 to 2025). "CFAP45 and PROM1 are found in both atypical and secondary ciliopathies, whereas TTC26, SCLT1, DNAJB11, DYNC2LI1, ALMS1, IFT80 and IFT74 are shared between primary and atypical ciliopathies." (PMID 37542408, 2023). "The four ciliopathy genes (BUBR1 [BUB1B], IFT80, KIF7 and TMEM216) we identified as modifiers of progenitor proliferation encode proteins localized to distinct ciliary compartments." (PMID 26206566, 2015). "We also observed that knockdown of ciliopathy genes ALMS1, BUBR1 [BUB1B], IFT80, NPHP1, NPHP8 [RPGRIP1L], TCTN2, TMEM216 and TUB retarded neuronal migration." (PMID 26206566, 2015). "This was indeed confirmed by a large screen from the Anton lab, where mouse in utero electroporation of a shRNA library of 30 known ciliopathy genes revealed cortical migration defects for as many as 17 of them, such as BBS1 (Bardet–Biedl syndrome protein 1) and IFT80 (Intraflagellar transport 80)." (PMID 36359777, 2022).
diabetes (1 paper, 2023). "We report here that streptozotocin (STZ)-induced type 1 diabetes mellitus (T1DM) dramatically increased Foxo1 expression in femoral fracture calluses, which thereby caused a significant decrease in the expression of IFT80 and primary cilia number." (PMID 37591875, 2023). "Our previous study showed that diabetes downregulates IFT80 expression levels and disrupts cilia formation in osteoblasts leading to defective fracture healing." (PMID 37591875, 2023). "In this study, we found that diabetes impairs fracture healing through Foxo1-mediated transcriptional inhibition of IFT80 expression and disruption of primary cilia formation in osteoblasts, thereby resulting in impaired osteogenesis." (PMID 37591875, 2023). "Thus, our findings demonstrate that diabetes impairs fracture healing through Foxo1 mediated inhibition of ciliary IFT80 expression and primary cilia formation, resulting in impaired osteogenesis." (PMID 37591875, 2023).
gastric cancer (1 paper, 2018). A primary or metastatic malignant neoplasm involving the stomach. "To further study the mechanism by which IFT80 promotes gastric cancer cell invasion, we next examined whether the overexpression of IFT80-enhanced invasion ability of SGC-7901 cells is associated with p75NGFR and MMP9." (PMID 30453504, 2018). "We established SGC-7901 and MKN-45 gastric cancer cell lines that stably overexpressed IFT80, as verified by quantitative reverse transcription-PCR, Western blot, and immunofluorescence." (PMID 30453504, 2018). "This study detected that the overexpression of IFT80 increased the expression of p75NGFR and MMP9 in SGC-7901 gastric cancer cells, indicating that IFT80 overexpression increased the invasion of gastric cancer." (PMID 30453504, 2018). "Our study has also shown that IFT80 was overexpressed in gastric cancer, and that overexpression of IFT80 increases the proliferation of SGC-7901 cells, but inhibits apoptosis." (PMID 30453504, 2018). "Here, we present the first evidence that IFT80 is significantly highly expressed in gastric cancer cells, and we also show that IFT80 increases the invasion and metastasis of gastric cancer by the upregulation of p75NGFR and MMP-9." (PMID 30453504, 2018). "Overexpression of IFT80 in the gastric cancer cell lines, SGC-7901 and MKN-45, led to lengthening cilia." (PMID 30453504, 2018). "To identify the expression pattern of IFT80, we first analyzed IFT80 expression in 48 clinical gastric cancer tissues by immunohistochemistry." (PMID 30453504, 2018). "IFT80 expression was found in higher levels in gastric cancer tumor tissue than in normal gastric tissue (indicated by the arrow)." (PMID 30453504, 2018). "We first detected an IFT80 expression pattern, and found that IFT80 was highly expressed in gastric cancer clinical samples." (PMID 30453504, 2018). "Our results indicated that IFT80 enhanced the invasion ability in gastric cancer via upregulation of MMP9 protein expression." (PMID 30453504, 2018). "Although the regulation of IFT80 has mainly been studied in osteoblasts, zebrafish photoreceptor cell death, mouse multifinger syndrome, and chondrocyte differentiation regulation, this report is the first to demonstrate the role of IFT80 in gastric cancer." (PMID 30453504, 2018). "The results showed that IFT80 was highly expressed in clinical gastric cancer." (PMID 30453504, 2018). "Therefore, in this study, our aim was to investigate the effects of IFT80 overexpression on the biological functions of gastric cancer, in which the invasion potential of cancer cells is essential for cancer metastasis." (PMID 30453504, 2018). "Until now, whether ift80 was expressed in gastric cancer cells and the mechanism of progress of gastric cancer have largely been unknown." (PMID 30453504, 2018). "Additionally, overexpression of IFT80 significantly improved proliferation and invasion, but inhibited apoptosis, in gastric cancer cells." (PMID 30453504, 2018). "MKN-45 gastric carcinoma cells were allowed to migrate through Matrigel-coated Transwell inserts into lower wells, and it was determined that overexpression of IFT80 promotes the invasion of MKN-45 cells, but treatment with PD90780 inhibits the invasion ability." (PMID 30453504, 2018). "Treatment with the p75NGFR antagonist PD90780 inhibited the increased invasion ability resulting from overexpression of IFT80 in SGC-7901 and MKN-45 gastric cancer cells." (PMID 30453504, 2018). "However, whether or not the IFT80 protein is associated with gastric cancer cell proliferation, metastatic infiltration, and cell apoptosis, is not clear." (PMID 30453504, 2018). "However, the role and mechanism of IFT80 in the invasion of gastric cancer is unknown." (PMID 30453504, 2018).
oral-facial-digital syndrome 1 (1 paper, 2023). "IFT88 overexpression led to upregulation of IFT80/81, two critical components of IFTB complex, and caused downregulation of OFD1 (oral-facial-digital syndrome 1), a ciliogenesis suppressor." (PMID 37485393, 2023).
osteoarthritis (1 paper, 2015). A noninflammatory degenerative joint disease occurring chiefly in older persons, characterized by degeneration of the articular cartilage, hypertrophy of bone at the margins and changes in the synovial membrane. "Our findings regarding the regulation of IFT80 in chondrocyte differentiation, cartilage formation, and Hh and Wnt signaling pathways, may open a new path to treat bone diseases including JATD, SRP, osteoarthritis by manipulating either IFT80 expression or related signaling pathways." (PMID 26098911, 2015).
respiratory failure (1 paper, 2015). The significant impairment of gas exchange within the lungs resulting in hypoxia, hypercarbia, or both, to the extent that organ tissue perfusion is severely compromised. "Furthermore, all affected individuals died from respiratory failure and a severe short rib phenotype which is not observed in individuals with IFT140, IFT172 or IFT80 mutations." (PMID 25361962, 2015).
infection (1 paper, 2016). The state of being infected such as from the introduction of a foreign agent such as serum, vaccine, antigenic substance or organism. "To further confirm that IFT80 was deleted after Ad-CMV-Cre infection, we performed immunofluorescence staining for IFT80 in OPCs from OSX;IFT80+/+ and OSX;IFT80f/f mice." (PMID 26996322, 2016).
IFT80 also shares sentences with these, for which no sentence is quoted: Osteopenia (2 papers); tumor (2); breast carcinoma (1); cancer (1); cranioectodermal dysplasia (1); cystic renal disease (1); fibrosis (1); genetic disease (1); lung adenocarcinoma (1); McKusick-Kaufman syndrome (1); orofaciodigital syndrome (1); pancreatic cancer (1); Respiratory insufficiency (1); retinal degeneration (1); retinal disease (1); Senior-Loken syndrome (1); skeletal dysplasia (1); type 1 diabetes mellitus (1).